DNAJC16 (DnaJ heat shock protein family (Hsp40) member C16)
Description:
Plays an important role in regulating the size of autophagosomes during the formation process.
Synonyms: ERdj8; KIAA0962
Tractability: Antibody: UniProt predicts a signal peptide or a membrane-spanning region. PROTAC: ubiquitination databases record sites on it; its protein half-life has been measured.
Gene: Protein-coding gene on chromosome 1 (15,526,813 to 15,592,379, forward strand). Ensembl gene ENSG00000116138.
Subcellular location: Endoplasmic reticulum membrane
Subcellular location (Human Protein Atlas): Vesicles
Gene Ontology:
Biological process: regulation of autophagosome size
Cellular component: endoplasmic reticulum membrane
Genetic constraint (gnomAD): Loss-of-function variants: 69 observed, 90.35 expected, observed/expected ratio (o/e) 0.76, 90% interval 0.63 to 0.93. The upper end of that interval is the gene's LOEUF score, 0.93, which puts it in group 3 of 6, group 1 being the genes least tolerant of losing a copy. Missense variants: 845 observed, 971.71 expected, observed/expected ratio (o/e) 0.87, 90% interval 0.82 to 0.92. Synonymous variants: 325 observed, 374.28 expected, observed/expected ratio (o/e) 0.87, 90% interval 0.79 to 0.95.
Homologues: Orthologues: chimpanzee DNAJC16 (99% identical), macaque DNAJC16 (98% identical), dog DNAJC16 (93% identical), rat Dnajc16 (90% identical), guinea pig DNAJC16 (89% identical), mouse Dnajc16 (88% identical), rabbit DNAJC16 (87% identical), pig DNAJC16 (79% identical), tropical clawed frog dnajc16 (75% identical), zebrafish dnajc16 (59% identical), zebrafish dnajc16l (55% identical), Drosophila melanogaster l(3)80Fg (15% identical), and 10 more. Paralogues in human: DNAJC13 (18% identical), DNAJC10 (13% identical), DNAJC21 (12% identical), DNAJC2 (10% identical), DNAJC11 (9% identical), DNAJC1 (9% identical), DNAJC14 (8% identical), DNAJC18 (8% identical), DNAJC9 (8% identical), DNAJC17 (8% identical), DNAJC25 (8% identical), DNAJC5 (8% identical), and 8 more.
Diseases named in the same sentence as DNAJC16 in open-access papers:
DNAJC16 is named in the same sentence as 6 diseases in open-access papers, as found by Europe PMC text mining. Sharing a sentence is not in itself a finding about the gene and the disease. The quoted sentences say what the papers report.
gout (1 paper, 2022). A condition characterized by painful swelling of the joints, which is caused by deposition of urate crystals. "Three LD blocks existed in chromosome 1 for the variants relating to gout, which were composed of genes DNAJC16, AGMAT (first block), PDZK1, CD160, NUDT17 (second block), TRIM46, MUC1, MTX1, and ASH1L (third block)." (PMID 36221101, 2022). "Surprisingly, the results showed that three variants of DNAJC16 and one variant of AGMAT were significantly associated with gout, which had not been found before, namely, rs7546668 (DNAJC16), rs12124078 (DNAJC16), rs7515244 (DNAJC16), and rs10927807 (AGMAT)." (PMID 36221101, 2022). "Surprisingly, variants on chromosome 1, such as rs7546668 (DNAJC16), rs10927807 (AGMAT), rs9286836 (NUDT17), rs4971100 (TRIM46), rs4072037 (MUC1), and rs2974935 (MTX1), showed significant associations with gout in both discovery and replication cohorts (all p-values < 1e−8)." (PMID 36221101, 2022). "This study performed a GWAS in a large sample size and found genes DNAJC16, AGMAT, NUDT17, TRIM46 MUC1, and MTX1 on chromosome 1 relating to gout disease." (PMID 36221101, 2022). "Surprisingly, variants on chromosome 1 located in genes DNAJC16, AGMAT, NUDT17, TRIM46, MUC1 and MTX1 showed significant associations with gout, which finding had not been reported before." (PMID 36221101, 2022).
Paget disease (1 paper, 2024). A malignant neoplasm composed of large cells with large nuclei, prominent nucleoli, and abundant pale cytoplasm (Paget cells). "For example, LPP is implicated in paget disease, DNAJC16 plays a crucial role in coordinating immune responses, and SUGT1 provides resilience against Haemonchus contortus." (PMID 38684985, 2024).
prostate carcinoma (1 paper, 2023). A carcinoma that arises from epithelial cells of the prostate gland. "Interestingly, the DNAJC16 gene is one of the chaperone families HSP40, which regulates AR and mediating sensitivity to chaperone inhibitors to aid in identifying new drug targets for efficacy in castration-resistant prostate cancer." (PMID 38136890, 2023).
infection (1 paper, 2014). The state of being infected such as from the introduction of a foreign agent such as serum, vaccine, antigenic substance or organism. "For instance, Dnaja2, Dnajb2, Dnajb12a, Dnajb12b, Dnajb14, Dnajc5ab, Dnajc5gb, Dnajc7, Dnajc16, and Dnajc26 were up-regulated only at 3 days after infection, but not at 14 days after infection; similarly, Dnajc28 was up-regulated only at 14 days after infection, but not at 3 days after infection." (PMID 25542027, 2014).
DNAJC16 also shares sentences with these, for which no sentence is quoted: hyperuricemia (1 paper); sarcoma (1).